CD4 (CD4 molecule)
Diseases named in the same sentence as CD4 in open-access papers (continued):
Sharing a sentence is not in itself a finding about the gene and the disease.
colitis (continued). "To further determine the impact of Ku70 deficiency on Treg function, we isolated CD45.2+ Tregs from WT and cKO mice and then transferred them along with naive CD45.1+CD4+ T cells into Rag1–/– recipient mice to establish adoptive transfer colitis models." (PMID 39446493, 2024). "In our study, we integrated bulk RNA-seq transcriptomic analysis with a gene regulatory network approach to thoroughly characterize conventional CD4+ T cells from the colonic lamina propria and the spleen using a transfer colitis mouse model." (PMID 38719901, 2024). "The naive and all primed cADSCs consistently reduced the frequency of CD4+ IL-17A+ Th17 cells increased by colitis induction, similar to the suppression pattern in Th1 cells, and especially cADSCs primed with colon homogenate significantly reduced Th17 cells." (PMID 39176394, 2024). "Some studies reported that anti-NKG2D antibodies can delay NK cell-mediated allergic airway inflammation, block CD4+T cell-mediated colitis, improve collagen-induced arthritis, and alleviate NKT cell-mediated acute hepatitis." (PMID 38282118, 2024). "In a murine model, naturally occurring CD8+CD28- Tregs and in vitro activated CD8+CD122+ T cells prevented CD4+CD45RBhi T cell-induced colitis." (PMID 39085655, 2024). "A 4.3-fold expansion in MLN B cell numbers was observed in colitis mice, and the co-transfer of MLN B cells along with CD4+ T cells increased colitis compared to the transfer of CD4+ T cells alone." (PMID 38785804, 2024). "In fact, CD4+CD25+ Tregs effectively prevent colonic inflammation in CD4+CD45RBhi T-cell-induced colitis." (PMID 39085655, 2024). "To explore the impact of EGCG treatment on the intestinal microenvironment in colitis, we performed a comprehensive analysis of various immune cells, including CD4+ T, CD8αβ+ T, CD79a+ B cells, and F4/80+ macrophages, using flow cytometry." (PMID 39116526, 2024). "The overall analysis of DEG suggests that colonic CD4+ T cells were more disturbed in colitis with several inflammatory immune responses activated, in contrast to splenic CD4+ T cells." (PMID 38719901, 2024). "In IELs, CD4+ T cell frequencies were significantly lower in the colitis group administered the probiotic mixture than in the colitis group not administered the mixture (p < 0.01)." (PMID 39201260, 2024). "Using these mouse models, we analyzed Treg cell generation, Treg cell transcriptomes, and Treg cell function in vitro as well as in adoptive CD4+ T cell transfer colitis." (PMID 39466314, 2024). "We established a bacterial antigen-specific colitis model induced by adoptive transfer of ovalbumin (OVA)-specific CD4+ T cells, followed by the intrarectal administration of Escherichia coli expressing OVA." (PMID 39403381, 2024). "In an experimental model of CD4+CD45+Rbhi-induced T cell transfer colitis, CA-MLCK mice exhibit more severe IBD symptoms." (PMID 39456702, 2024). "It is a haptenising molecule with no inherent antigenicity, yet its administration elicits a Th1-mediated immune reaction, including the infiltration of CD4+ T-cells, neutrophils and macrophages, resulting in transmural colitis mirroring CD in humans." (PMID 38543070, 2024). "Specifically, it was found that the expression of Ifng, Il12rb1, and Il12rb2 was impaired in colonic CD4+ T cells of Il21r−/− mice during C. rodentium–induced colitis." (PMID 38498592, 2024). "This switch in homing preferences is evidenced by a substantial proportion of activated gut CD4+ T cells expressing both skin and gut homing receptors, as seen in animal models of ileitis or colitis and in cases of human Crohn’s disease." (PMID 38654394, 2024). "Here, the DSS-induced colitis mice showed a remarkable imbalance with a significant increase in CD4+CCR6+ Th17 cells and a significant decrease in CD4+Foxp3+ Treg cells in the mesenteric lymph nodes (MLNs)." (PMID 38202824, 2024).
colitis (continued). "Under inflammatory conditions in the colon, modulation of TLR and IFN pathways in iNKT lymphocyte, CD4+ T cell, and B cell subpopulations have been shown to contribute to smoke-induced colitis improvement." (PMID 39051349, 2024). "In this adoptive transfer model of colitis, homeostatic expansion of donor CD4+ T cells is requisite for disease induction." (PMID 37962568, 2024). "In this study, chronic T cell-mediated colitis was induced by adoptively transferring CD4+CD45RBhigh splenic T cells from C57BL/6 WT donor mice into Rag1tm1Mom mice." (PMID 38255320, 2024). "There was a significant increase in the frequencies of CD4+CCR7−Foxp3+ and CD4+CCR7−IL-10+ mTreg cells and a significant decrease in CD4+CCR7−IL-17A+ mTh17 cells in the MLNs of the mice with DSS-induced experimental colitis." (PMID 38202824, 2024). "Under similar conditions, orally injecting axenic Blastocystis ST7 into DSS-induced colitis mice exacerbated the severity of colitis by increasing the proportion of pathogenic bacteria and inducing pro-inflammatory IL-17A and TNF-α-producing CD4+ T cells." (PMID 38087868, 2024). "Intrarectal administration of the haptenating agent TNBS induces a severe CD4+ T cell-dependent colitis in mice, resulting in increased permeability and inflammation." (PMID 38839750, 2024). "Using a well-established and physiologically relevant murine model of Citrobacter rodentium–induced colitis, the mechanisms by which the IL-21/IL-21R signaling axis regulates colitis by enhancing the IL-12 responsiveness of CD4+ T cells were explored." (PMID 38498592, 2024). "Whereas, only 30 DEG were found in spleen CD4+ T cells from colitis mice compared to the respective normal condition." (PMID 38719901, 2024). "The findings of the current study provide novel insights into the mechanisms by which functional IL-21/IL-21R signaling regulates IL-12 responsiveness by promoting IL-12Rβ2 expression in CD4+ T cells, leading to colitis." (PMID 38498592, 2024). "After this experiment, primed cADSCs were co-cultured for 3 days with CD4+ T-helper (Th) cells derived from the spleen of colitis mice stimulated with anti-CD3/CD28-coated beads, followed by flow cytometry measurement of Th cell proliferation." (PMID 39176394, 2024). "Similar frequencies and numbers of wild-type (WT) and NCOR1-cKO Treg cells within small intestinal intraepithelial lymphocyte (SI-IEL) and lamina propria cell (SI-LP) populations in adoptive CD4+ T cell transfer colitis." (PMID 39466314, 2024). "An intricate gene regulatory network was observed in colonic CD4+ T cells under inflammatory conditions in a colitis mouse model." (PMID 38719901, 2024). "Clinically, CLA also ameliorated DSS- and CD4+-induced colitis through a PPAR γ-dependent mechanism." (PMID 39062500, 2024). "Research indicates that using dextran sulfate sodium (DSS) to aggravate colitis in OS mouse models leads to amplified skin inflammation, with a notable increase in circulating CD4+ T cells expressing both skin- and gut-homing receptors (CCR4 and CCR9)." (PMID 38654394, 2024). "An interesting example of this is a recent study using a colitis model induced by transferring naïve CD4+ T cells into Rag2-/- mice." (PMID 38719901, 2024). "Rag1−/− mice reconstituted with GPR65 I231L or GPR65 knockout (KO) CD4+ T cells demonstrate more severe colitis phenotypes compared to those reconstituted with GPR65 wild-type (WT) CD4+ T cells." (PMID 39028811, 2024). "In our study, Th1 cells are the most affected subsets, and EGCG markedly affects effector CD4+ T cell populations under the colitis condition, especially Th1 cells." (PMID 39116526, 2024). "This inhibition suppresses the activation of the JAK/STAT signaling pathway, disrupting the differentiation of naive CD4+ T cells and inhibiting the development of colitis in a T cell transfer-induced colitis model." (PMID 38830900, 2024).
colitis (continued). "The antibody-mediated abrogation of IL-21/IL-21R signaling led to the impaired expression of IFN-γ by mucosal CD4+ T cells from human subjects with colitis, suggesting an IL-21/IL-21R–triggered positive feedback loop of the TH1 immune response in the colon." (PMID 38498592, 2024). "Another study showed that TGF-β1-modified exosomes (TGF-β1-Exs) induce CD4+ Foxp3+ Tregs, reducing the proportion of Th17 in lymphocytes at the site of inflammation, mitigating the inflammatory response in a mouse model of colitis." (PMID 39185411, 2024). "Adoptive transfer of WT CD4+ T cells into TSLPR-deficient Rag1KO mice (Rag1–/–Tslpr–/– or Rag1KOTslprKO) caused fulminant, lethal colitis." (PMID 37427591, 2023). "When compared to the model group, curcumin reduced mortality in mice with colitis, inhibited IκB, induced the nuclear translocation of NF-κB into the epithelial nucleus, and reduced the infiltration of CD4+ T-cells." (PMID 37719857, 2023). "Together, these results identify TSLP as a major regulator of homeostatic CD4+ T cell expansion in the adult colon, thereby preventing lethal colitis." (PMID 37427591, 2023). "An increased proportion of colonic T cells co-expressing IFNγ granzyme B and perforin was observed in CPI colitis, especially in CD4+ and CD8+ T cells." (PMID 37872166, 2023). "NSG mice receiving eEF2K KO CD4+ T cells (eEF2K KO group) underwent significant weight losses, as compared to the WT group, and colitis was more severe in the eEF2K KO group than in controls, as evidenced by their shortened colons." (PMID 37875468, 2023). "In a colitis model experiment generated by DSS, CD4+T cells driven by Pg exacerbated the colitis condition by elevating the Th17/Treg cells ratio in both the colon and LPLs." (PMID 37904683, 2023). "As such, microbiome-depleting antibiotic treatment prevented lethal colitis in Rag1KOTslprKO animals that received CD4+ T cell transfer." (PMID 37427591, 2023). "In the Th2-dominant oxazolone-induced colitis mouse model, IL-9 expression is increased throughout the intestinal tract, and the number of intestinal and splenic IL-9+ CD4+ T-cells is higher than in control mice." (PMID 36769019, 2023). "The present study showed that the protective effect of KC3 against DSS-induced colitis is accompanied by the restoration of Treg cell populations while reducing CD4+ T cells in the mucosal lamina propria and MLNs." (PMID 37110390, 2023). "A previous study suggested that B. vulgatus increased the number of regulatory/anti-inflammatory CD4+ T cell subsets in a mouse model of T cell-induced colitis." (PMID 38033588, 2023). "For example, transfer of the CD4+CD45RBhiNlrp12−/− T cells into the immunodeficient mice exacerbated severe colitis and showed that NLRP12 was an intrinsic negative regulator of T cell activation." (PMID 37191444, 2023). "IL23 blockade reduced the number of IFNγ producing CD4+ T cells in the colon in CPI colitis and especially IFNγ/TNFα co-producing cells." (PMID 37872166, 2023). "Administration of IPA attenuates pro-inflammatory (CD4+IFNγ+IL10−) T cells and increases anti-inflammatory (CD4+IFNγ−IL10+) T cells in the colon in a mouse model of colitis." (PMID 37298145, 2023). "TRPA1 is protective in a T-cell-mediated colitis model by inhibiting the TRPV1 activity in CD4+ T cells." (PMID 36875034, 2023). "TSLP signaling in circulating cells prevents CD4+ T cell–induced lethal colitis in Rag1KOTslprKO mice." (PMID 37427591, 2023). "In mouse DSS colitis model, both expression and function of the KCa3.1 channel are upregulated in the CD4+ T lymphocytes in the mesenteric lymph node, which is a driving force of the enhanced production of inflammatory cytokines, such as IFNγ." (PMID 36459135, 2023). "T cell specific-HK2 deficiency partially recovers intestinal inflammation in a spontaneous colitis model of IL-10 knockout (KO) mice, although HK2-deficient CD4+ T cells appear to have normal proliferation, viability, activation and differentiation in vitro." (PMID 37809060, 2023).
colitis (continued). "The increase in STAT3 expression in eEF2K knockout CD4+ T cells prompted us to explore the role of this transcription factor in the eEF2K-mediated regulation of colitis." (PMID 37875468, 2023). "Based on evidence from animal models with spontaneous or experimentally induced colitis, CD and even ulcerative colitis (UC) have been mainly attributed to T cell-mediated inflammation, particularly mediated by CD4+ T cells responding to luminal antigens." (PMID 37108957, 2023). "KFX effectively suppresses TNBS-induced colitis by inhibiting the activation of NF-κB p65 and regulating the ratio of CD4+/CD8+." (PMID 37427322, 2023). "TCRβ-/- mice transferred with CD4-Cu2++DSF T cells had lower IL-17A and IL-17F mRNA levels in DSS-induced colitis than those transferred with CD4 control." (PMID 37284442, 2023). "During naive CD4+ T cell transfer-mediated colitis, CD4+ T cells are in close contact with colonic CX3CR1+ phagocytes that present bacterial-derived Ags." (PMID 38274786, 2023). "The lethal colitis was rescued by parabiosis between Rag1KOTslprKO and Rag1KO animals and wild-type dendritic cells (DCs) suppressed CD4+ T cell–induced colitis in Rag1KOTslprKO mice." (PMID 37427591, 2023). "Flow cytometry analysis demonstrated that, after the development of colitis, the eEF2K knockout group had higher populations of IL-17A+ CD4+ T cells in the colons compared to the WT group." (PMID 37875468, 2023). "As the development of colitis in this model is induced by the transfer of naïve CD4+ T cells to lymphopenic recipients, it is often used for the study of CD4+ T cell functions in the intestine." (PMID 38012544, 2023). "Several colitis models indicated that CD8+T cells-mediated destruction of intestinal epithelial cells led to the damage of the mucosal barrier, and then activated CD4+T cells and other immune cells, ultimately caused the intestinal inflammation." (PMID 37106335, 2023). "They clearly showed that ILC3s express major histocompatibility complex class II (MHCII) and such MHCII+ ILC3 play important roles to control dysregulated CD4 T cells during colitis." (PMID 37901813, 2023). "This induction revealed the anti-inflammatory action of IFN-γ as there was reduction of colitogenic CD4+ T cells during chronic bacterial-driven colitis offering protection against colitis." (PMID 36911685, 2023). "Consistently, Smad7-deficient DCs promoted the differentiation of naive CD4+ T cells into Foxp3+ Tregs, and mice with Smad7-deficient DCs developed less severe DSS-induced colitis compared to controls." (PMID 36714553, 2023). "To examine the roles of microRNAs in the development of colitis, we conducted the RNA-sequencing studies using RNA derived from normal and colitogenic CD4+ T cells." (PMID 39132043, 2023). "Transfer of naive CD4+ T cells into immunodeficient Rag2-knockout (Rag2−/−) mice induces colitis and small bowel inflammation." (PMID 37301920, 2023). "Specifically, the increase of CD4+ T lymphocytes is usually found in subjects treated with anti-CTLA-4, while the increase of CD8+ is associated with anti-PD-1 colitis." (PMID 37511260, 2023). "In vivo and in vitro investigations showed that microbiota-induced IL-10-secreting intestinal B cells improved chronic LP CD4+ T cell-mediated colitis by activating TLR2/MyD88/PI3K p110δ signaling." (PMID 37836654, 2023). "Although neuronal TRPA1 increases acute inflammation, non-neuronal TRPA1 activation is anti-inflammatory, and TRPA1 in CD4+T cells reduces T cell-mediated colitis." (PMID 36875034, 2023). "Because immune regulation is crucial for the development and progression of colitis, especially IL-17 secreted by CD4+ T cells 36, we investigated the effect of DSF and Cu2+ on IL-17 secretion by CD4+ T lymphocytes following DSS treatment." (PMID 37284442, 2023).
colitis (continued). "Conversely, prior ST7 infection exacerbated the severity of colitis by increasing the proportion of pathogenic bacteria and inducing pro-inflammatory IL-17A and TNF-α-producing CD4+ T cells." (PMID 36793854, 2023). "Concerning the significant therapeutic effect of CD73-expressing ERCs on colitis, we further evaluated its immune modulation role in CD4+ cell differentiation." (PMID 37180168, 2023). "Diet (high methionine)-induced hyperhomocysteinemia exacerbated DSS-induced colitis in rats, and homocysteine promoted CD4+ T cell differentiation (lamina propria lymphocytes in the colonic mucosa of Wistar rats) into Th17 cells." (PMID 36768979, 2023). "Antibiotic treatment markedly reduced the severity of CD4+ T cell–induced colitis in Rag1KOTslprKO and Rag1KO mice." (PMID 37427591, 2023). "On one hand, elevated titer of anti-flagellin IgG has been associated with Crohn’s disease and, moreover, flagellin-specific CD4+ cells have been reported to induce colitis in SCID mice." (PMID 36880647, 2023). "The results showed that both primary and immortalized cADSCs inhibited the proliferation of Th cells from mice with colitis and canine CD4+ Th cell and CD8+ CTL proliferation." (PMID 38139314, 2023). "Adoptive transfer of CD4+Lrig1+ T cells alleviates autoimmune symptoms in colitis and lupus nephritis mouse models." (PMID 37666819, 2023). "The role of DSF and Cu2+ in regulating CD4+ T cells in the development of DSS-induced colitis was investigated." (PMID 37284442, 2023). "In this study, compared with L. lactis, oral administration of LL-IL-27 showed a stronger protective effect against CD4+CD45RBhi T-cell transfer-induced colitis by alleviating intestinal damage and promoting IL-10 expression in the colon." (PMID 37049407, 2023). "In mouse models of colitis, intestinal microbes drive inflammation, in part, by stimulating microbiota-reactive CD4+ T cells." (PMID 36602872, 2023). "Fittingly, it has been observed that when naïve CD4+ T cells were transferred from healthy mice into immunocompromised mice, colitis was induced." (PMID 37901813, 2023). "Transfer of naive T (Tnai) cells (CD4+Foxp3−CD44loCD62Lhi) into Rag1−/− recipients led to a wasting disease with colitis within 4 weeks." (PMID 37600496, 2023). "Tr1 cells prevent colitis in adoptive transfer models, and pathogenic colitis-inducing Th17 cells are suppressed by both Foxp3+ and Foxp3- IL10-producing CD4+ T-cells." (PMID 37654482, 2023). "The transcription factor interferon regulatory factor 5 (IRF5) aggravates experimental colitis by increasing the CD4 T-cell expression of Th1- and Th17-related cytokines and reducing the expression of Th2-related cytokines." (PMID 36769019, 2023). "This is a more complex question in relation to colitis than retinitis since the colon has a constitutive population of immune cells including CD4 Teff and Treg (up to 30% of the total colonic CD4 T cell population in SPF-housed mice are Treg45)." (PMID 36690619, 2023). "In C. rodentium-induced colitis, goblet cell-derived RELMβ recruits CD4+ T cell to the infected intestine." (PMID 36691020, 2023). "Colitis induction resulted in an overall moderation of the percentage and the absolute numbers of the CD4+ population in mLN and the spleen." (PMID 37571230, 2023). "More specifically, A. muciniphila supplementation has been proven beneficial against CD4 T cell transfer model of colitis in animals through the upregulation of RORγt+Foxp3+ T regulatory 17 cells." (PMID 38107848, 2023). "In particular, PGD2 has been recognized as a tumor suppressor via the PGD2 receptor in colitis-associated colon cancer, and PGI2 is capable of recruiting CD4+ T cells in MHC class II–expressing murine lung cancer cells." (PMID 37529399, 2023). "The antigens from Akk are able to reprogram naïve CD4+ T cells into the Tregs lineage, expand preexisting microbe-specific Tregs, and limit wasting disease in the CD4+ T cell transfer model of colitis." (PMID 36835309, 2023).